MPO (myeloperoxidase)
Diseases named in the same sentence as MPO in open-access papers (continued):
Sharing a sentence is not in itself a finding about the gene and the disease.
Shock (4 papers, 2015 to 2025). The state in which profound and widespread reduction of effective tissue perfusion leads first to reversible, and then if prolonged, to irreversible cellular injury. "Indeed, Carr and colleagues showed that circulating MPO is elevated in patients with septic shock and associated with organ failure and mortality in critically ill patients despite comparable neutrophil counts in septic shock and non-septic patients." (PMID 32050431, 2020). "Moreover, C5aR1-knock-down animals has a lower MPO level in lung of mice with polytrauma and hemorrhagic shock." (PMID 38165570, 2024). "Similarly, VPA showed protection from lung inflammation by decreasing serum IL-6 and TNF-α levels, as well as MPO activity significantly in pulmonary tissue by amelioration of lung damage in a rat model of septic shock or acute lung injury." (PMID 25938838, 2015).
thyroid (4 papers, 2014 to 2020). "The anti-thyroid drug propylthiouracil (PTU) is associated with production of MPO-ANCA in up to 30% of patients, with some patients developing MPO-AAV." (PMID 32373109, 2020).
uremia (4 papers, 2015 to 2022). A clinical syndrome associated with the retention of renal waste products or uremic toxins in the blood. "It is possible that reduction in serum concentration of MPO after successful kidney transplantation is due to attenuation of oxidant and inflammatory states induced by the uremia." (PMID 26648662, 2015). "In CKD further, uremia results in production of cyanate in the presence of hydrogen peroxide (H2O2) and myeloperoxidase (MPO) mediates carbamylated protein synthesis that combines with high density lipoprotein (HDL)." (PMID 28178330, 2017). "The substantial neutrophil degranulation and intracellular reduction of key antibacterial proteins such as MPO, NE, and MMP-9 may result from persistent immune activation by uremia, the HD procedure, or the low-grade chronic inflammation seen in HD patients." (PMID 36284314, 2022).
ZIKV infection (4 papers, 2017 to 2025). "Post-ZIKV infection, concentrations of plasma MPO continued to be higher in SIV+ZIKV+ animals in comparison to SIV-ZIKV+ animals." (PMID 40103823, 2025). "Post-ZIKV infection, concentrations of plasma MPO continue to be significantly higher in SIV+ZIKV+ animals in comparison to SIV−ZIKV+ animals." (PMID 39229223, 2024). "To assess neutrophil function, we evaluated plasma concentrations of myeloperoxidase (MPO), a neutrophil granule and marker of inflammation, during the first 4 days of ZIKV infection." (PMID 39229223, 2024). "In accordance, ZIKV infection induced a similar increase in MPO activity and production of chemokines and cytokines in the brain of vehicle- and memantine-treated ZIKV-infected mice." (PMID 28442607, 2017). "Interestingly, prior to ZIKV infection, elevated levels of MPO were detected in 5/6 SIV+ animals while lower concentrations of MPO were detected in 7/7 SIV− animals." (PMID 39229223, 2024). "Our data showed that massive inflammation was found at the peak of ZIKV infection in the brain of ZIKV-infected IFN-α/βR−/− mice, as indicated by elevated levels of MPO activity and inflammatory mediators." (PMID 28442607, 2017). "The staining pattern of MPO showed no obvious difference between the presence or absence of pregnancy or ZIKV infection; that is, MPO was sporadically found in the corpus luteum but not in the primary follicles." (PMID 39998269, 2025).
acute liver failure (3 papers, 2018 to 2024). Rapid deterioration of liver function causing encephalopathy and coagulopathy. "Fittingly, in MerTK-deficient mice acute liver failure (ALF) due to APAP administration is aggravated and associated with a reduced number of hepatic macrophages and increased MPO+ neutrophils." (PMID 31798592, 2019).
airway hyperresponsiveness (3 papers, 2020 to 2023). "In the neutrophilic asthma model, treatment with DNase I or CI-amidine can reduce the expression of MPO and CitH3, decrease airway hyperresponsiveness, alleviate the accumulation of inflammatory cells and mucus obstruction, and mitigate inflammation-induced damage." (PMID 38283037, 2023). "In contrast, Ceylon type LO inhalation might have an irritant effect (e.g., increased airway hyperresponsiveness and MPO activity) on the inflamed airways, and therefore should be avoided." (PMID 32759721, 2020). "Our in vivo study showed that Nec-1 could alleviate airway hyperresponsiveness in OVA/CFA mouse model, and also reduced the level of NETs, total protein concentration and MPO activity in BAL as well." (PMID 32391007, 2020).
alveolitis (3 papers, 2018 to 2021). "Indeed, this herbal medicine can ameliorate pulmonary lesions as it downregulates alveolitis and the Ashcroft score, the underlying mechanism for this might relate to the downregulation of MPO, α-SMA, HYP, collagen I, collagen III, and inflammatory factors (TNF-α, IL-1β, and IL-6)." (PMID 34349830, 2021). "Radiation insult to the lungs resulted in neutrophil accumulation indicated by the combined alveolitis score, which in turn resulted in significant overexpression of MPO saline treated group." (PMID 33343356, 2020).
amebiasis (3 papers, 2017 to 2025). A parasitic infectious disorder caused by amoebas. "While EhA1 EV stimulation caused elevated myeloperoxidase (MPO) release by both monocytes and neutrophils, EhB2 EV stimulation did not, indicating the protective role of MPO during amebiasis." (PMID 40208874, 2025).
B-cell acute lymphoblastic leukemia (3 papers, 2015 to 2025). A neoplasm of lymphoblasts committed to the B-cell lineage, typically composed of small to medium-sized blast cells. "In hematological malignancies, MPO expression holds prognostic significance in B-cell acute lymphoblastic leukemia, where higher levels correlate with relapse and reduced event-free survival." (PMID 41303900, 2025).
brain tumors (3 papers, 2023 to 2025). "Although it is likely that MPO staining within macrophages partially reflects enhanced phagocytosis of neutrophils, MPO transcript is also detectable in brain tumour MDMs and peripheral monocytes at comparable levels to neutrophils." (PMID 36725935, 2023). "Our current study, which focused exclusively on grade 4 diffuse gliomas, the most aggressive primary brain tumors, revealed that a nomogram based on COL22A1, IGFBP2, and MPO expression can reliably evaluate patient prognosis." (PMID 37737709, 2023).
bronchiolitis (3 papers, 2021 to 2025). Inflammation of the bronchioles characterized by swelling of the bronchioles and mucus accumulation. "Similarly, in a study of 18 patients with MPO-ANCA-ILD, UIP was the most common pattern observed (56%) and often included bronchiolitis, lymphoid hyperplasia, DIP, and OP." (PMID 40649005, 2025). "In MPO‐ANCA‐positive interstitial pneumonia, the presence of bronchiolar lesions is frequently reported from HRCT images, and histopathological findings suggestive of bronchiolitis are frequently seen." (PMID 40070290, 2025).
chronic pancreatitis (3 papers, 2012 to 2025). A chronic inflammatory process causing damage and fibrosis of the pancreatic parenchyma. "Numerous MPO-positive neutrophiles and Mac-3 positive macrophages were observed in the pancreas of caerulein induced chronic pancreatitis mice; while markedly decreased MPO and Mac-3 positive cells were observed in sulindac treated chronic pancreatitis mice." (PMID 22920325, 2012).
cryptosporidiosis (3 papers, 2020 to 2023). Intestinal infection with organisms of the genus Cryptosporidium. "In conclusion, our exploratory study describes MPO as a potential biomarker for intestinal-brain axis dysfunction that is relevant in the context of enteric infections and undernutrition in our murine models of protein deficiency and cryptosporidium infection." (PMID 37150212, 2023). "SAA and MPO serum levels were significantly higher after dPD and Cryptosporidium infection compared to uninfected nourished controls, confirming systemic inflammation." (PMID 37150212, 2023).
delirium (3 papers, 2022 to 2025). A disorder characterized by confusion; inattentiveness; disorientation; illusions; hallucinations; agitation; and in some instances autonomic nervous system overactivity. "Multivariable logistic regression analysis revealed that increased postoperative MPO concentration was independently associated with postoperative delirium development, and negatively correlated with lower baseline serum AC." (PMID 35175161, 2022). "Of note, when controlling for variables significant in univariate comparisons, only patients with higher postoperative MPO levels remained at increased risk of postoperative delirium development." (PMID 35175161, 2022). "Univariate analysis showed the patients with increased pre- and postoperative MPO levels had a higher risk of postoperative delirium development comparing to patients with lower MPO concentrations." (PMID 35175161, 2022). "Upon activation, neutrophils can facilitate the release of myeloperoxidase, proteolytic enzymes, and oxygen, which in turn cause damage to the blood-brain barrier, inflict damage to brain, accelerate apoptotic rate, thereby inducing delirium." (PMID 39949395, 2024). "According to univariate analysis, both higher pre- and postoperative MPO levels were associated with post-surgery delirium, albeit, multivariable logistic regression model indicated that only MPO concentration raised after the intervention was independently associated with postoperative delirium." (PMID 35175161, 2022). "The primary objective of the current study is to assess whether increased pre- and postoperative myeloperoxidase (MPO) levels are associated with postoperative delirium in the population of cardiac surgery patients." (PMID 35175161, 2022). "The primary objective of the current study is to assess whether increased pre- and postoperative MPO levels are associated with postoperative delirium in the population of cardiac surgery patients." (PMID 35175161, 2022). "Therefore, it can be hypothesized that individuals with decreased baseline AC experience higher peak of MPO post-surgery due to less efficient antioxidative mechanisms, which in turn contributes to postoperative delirium development." (PMID 35175161, 2022). "Serum MPO-DNA and CitH3 were both numerically higher, though not significantly different between the delirium groups." (PMID 39737468, 2025). "Levels of MPO-DNA and CitH3 were not significantly higher in delirium, only numerically [(0.255 versus 0.210 optical density, P = 0.054) and (11.48 versus 8.41 ng/ml, P = 0.087), respectively]." (PMID 39737468, 2025).
dermatomyositis (3 papers, 2019 to 2023). Dermatomyositis (DM) is a type of idiopathic inflammatory myopathy characterized by evocative skin lesions and symmetrical proximal muscle weakness. "Enriched genes including S100A12, MPO (myeloperoxidase), S100A8, CXCL10, S100A9, CD244, CD244,and TLR7 have been linked to dermatomyositis." (PMID 38137330, 2023).
endophthalmitis (3 papers, 2011 to 2025). An infectious process affecting the internal structures of the eye. "In the HVIP1 vitreous, there were a number of significant correlations identified: CRP/Myoglobin, IGFBP-4/SAA, IGFBP-4/VCAM-1, and VCAM-1/SAA in the endophthalmitis group; MPO/NGAL, CRP/SAA, and Cystatin C/Myoglobin in controls; and NGAL/MMP-9 in both groups." (PMID 40563988, 2025). "In the patient sera, MMP-9, MPO, Calprotectin, NGAL, SAA (HVIP1), and MCP-1 (HIP1) were all significantly elevated in endophthalmitis samples, which was unexpected as pathology was thought to be localised with minimal systemic effects." (PMID 40563988, 2025).
esophageal squamous cell carcinoma (3 papers, 2020 to 2021). Esophageal squamous cell carcinoma (ESCC) is a type of esophageal carcinoma (EC) that can affect any part of the esophagus, but is usually located in the upper or middle third. "Myeloperoxidase (MPO)+ neutrophils releasing interleukin-17 (IL-17) are a favorable prognostic factor in esophageal squamous cell carcinoma (ESCC)." (PMID 32488850, 2020).
gastroesophageal reflux (3 papers, 2022 to 2024). "In this study, the stimulation of NADPH oxidase (NOX2 and p47phox) and MDA and MPO increased due to reflux esophagitis, whereas SC treatment significantly reduced the index related to increased oxidative stress." (PMID 35027935, 2022).
giardiasis (3 papers, 2018 to 2022). An infection of the small intestine caused by the flagellated protozoan giardia lamblia. "Giardiasis was associated with higher faecal MPO and AAT concentrations in the stool samples of the children." (PMID 30133067, 2018). "Giardiasis was found to be significantly associated with MPO (Coefficient = 0.55; 95% CI = 0.15, 0.95; P‐value = 0.008) and AAT concentrations (Coefficient = 0.34; 95% CI = 0.04, 0.63; P‐value = 0.03)." (PMID 30133067, 2018). "This prospective longitudinal study found that giardiasis was significantly associated with faecal MPO and AAT concentrations of children under 2 years." (PMID 30133067, 2018). "Together, this suggests that SG has no major role in granulocyte recruitment and the activity of MPO and NE during the Giardia-infection." (PMID 34335577, 2021). "Those with giardiasis had higher median values of MPO (P‐value = 0.001) and AAT (P‐value = 0.04) relative to children without giardiasis." (PMID 30133067, 2018).
Graves disease (3 papers, 2019 to 2024). Graves' disease is an autoimmune disorder that leads to overactivity of the thyroid gland (hyperthyroidism).It is caused by an abnormal immune system response that causes the thyroid gland to produce too much thyroid hormones. "It has been reported that MPO-ANCA was detected in 37.5% of patients with Graves’ disease being treated with propylthiouracil." (PMID 34451967, 2021). "Furthermore, in patients with autoimmune thyroid disorders, ANCA positivity was detected in 28% of those with Graves’ Disease (GD) and 9% of those with HT, with only one GD patient showing MPO positivity." (PMID 39518417, 2024). "We report a 19-year-old woman with Graves’ disease on PTU presented fever, polyarthralgia, and lung hemorrhage with high titer of MPO-ANCA." (PMID 31027105, 2019). "Blood test results showed elevated levels of myeloperoxidase (MPO)-ANCA and proteinase 3 (PR3)-ANCA, which were negative before the patient had received treatment for Graves’ disease, suggesting the presence of propylthiouracil-induced AAV." (PMID 34451967, 2021). "Her serum myeloperoxidase-ANCA and proteinase 3-ANCA levels, which were negative before the Graves’ disease treatment, were elevated." (PMID 34451967, 2021).
helminth infection (3 papers, 2014 to 2021). "Helminthiasis, MPO, biomarkers indicative of micronutrient deficiencies and inflammation at age 6, 9, and 12 months." (PMID 33600460, 2021).
Hematochezia (3 papers, 2018 to 2025). The passage of fresh (red) blood per anus, usually in or with stools. "The results showed that S1PR2 blockage significantly reduced the body weight loss and colon length shortening, exhibiting much lower MPO activity and hematochezia score, meanwhile ameliorating mucosal inflammatory cell infiltration and mucosal epithelium disruption." (PMID 29854830, 2018).
Hematuria (3 papers, 2022 to 2024). The presence of blood in the urine. "Here, we report a case of myeloperoxidase (MPO) ANCA-associated RLV in a young adult woman in Japan presenting chronic hematuria and newly overt proteinuria." (PMID 35233326, 2022). "In agreement with our data, which indicate the critical role of neutrophils during hematuria, it has been demonstrated that large numbers of myeloperoxidase (MPO)-immunoreactive neutrophils can be detected in the lamina propria and uroepithelium layers after SCI." (PMID 37489403, 2023).
hepatoblastoma (3 papers, 2021 to 2022). Hepatoblastoma (HB) is a malignant hepatic tumor and is the most common pediatric liver cancer. "For instance, in 48 Caucasian children with hepatoblastoma and 180 healthy controls, Pakakasama and colleagues found that a polymorphism (G to A) located in the myeloperoxidase (MPO) gene promoter was associated with decreased hepatoblastoma risk." (PMID 35986847, 2022). "They demonstrated that MPO-463 G>A was associated with the reduced susceptibility of hepatoblastoma." (PMID 34367972, 2021).
IgA vasculitis (3 papers, 2022 to 2024). "In this case, we presented a patient with suspected PTU-induced IgA vasculitis with elevated levels of anti-PR3 when compared to anti-MPO antibodies." (PMID 38957824, 2024). "A punch biopsy of the medial leg demonstrated IgA vasculitis and autoimmune antibody analysis revealed increased levels of anti-proteinase 3 antibodies compared to anti-myeloperoxidase antibodies." (PMID 38957824, 2024). "We present a case of PTU-induced IgA vasculitis characterized by elevated levels of anti-PR3 antibodies, which were higher than anti-MPO antibodies." (PMID 38957824, 2024). "Blood MPO-DNA levels are discussed as a biomarker of the early response against the SARS-CoV-2 infection, and elevated levels have also been detected in the sera of patients with IgA vasculitis." (PMID 36078028, 2022).
kidney (3 papers, 2015 to 2024). "Instead, recruitment of inflammatory neutrophils into kidney, followed by in situ activation, was the essential element in kidney damage since loss of neutrophil MPO abolished inflammation and fibrosis (vide supra)." (PMID 26720402, 2015). "Prostatic tissues from rats with LPS-induced prostatitis and low level of testosterone showed a higher MPO activity compared to those with normal androgen status." (PMID 30233581, 2018). "Pre-treatment with the investigated compounds prevented an L-arginine-induced increase in serum and tissue kidney damage markers and, additionally, decreased the levels of inflammation-related parameters (TNF-α and nitric oxide concentrations and myeloperoxidase activity)." (PMID 38256015, 2024).
kidney stones (3 papers, 2013 to 2026). "Neutrophils release oxidative and inflammatory mediators, such as myeloperoxidase, which not only damage renal epithelial cells but also promote crystal formation and growth in urine, further increasing the risk of kidney stones." (PMID 39963279, 2025). "The protein list contained typical components of kidney stones such as prothrombin, THP, calgranulin A, calgranulin B, and myeloperoxidase." (PMID 23874695, 2013).
Liver abscess (3 papers, 2017 to 2025). A circumscribed area of pus or necrotic debris in the liver. "In the hamster, a chronic susceptible model to ALA, the reduction in the neutrophils’ MPO activity as well as the reduction in ROS and NO production could be the mechanisms that could participate in the amoebic liver abscess resolution." (PMID 37446394, 2023).
liver failure (3 papers, 2024 to 2025). A liver disease characterized by the liver losing or has lost all of its function. "Another study based on liver failure in mice reported that myeloperoxidase (MPO) and MDA levels were reduced, and SOD and CAT activities were improved with myricetin at doses of 50 and 100 mg/kg pretreatment." (PMID 40362425, 2025). "Studies have shown that NET markers such as plasma MPO-DNA levels can serve as prognostic markers for predicting HBV-related liver failure and assist in clinical drug selection for patients with HBV-related liver failure." (PMID 41156629, 2025).